CXCL1 (C-X-C motif chemokine ligand 1)
Diseases named in the same sentence as CXCL1 in open-access papers (continued):
Sharing a sentence is not in itself a finding about the gene and the disease.
liver disease (18 papers, 2013 to 2025). "Cxcl1 has been reported to be associated with the recruitment of neutrophils and the severity of liver disease during liver injury." (PMID 38130716, 2023). "CXCL-1 is a potent agonist for CXCR2 which recruits neutrophils to the site of inflammation or injury during liver disease, and plasma levels of CXCL1 are associated with liver fibrosis in HCV-infected patients." (PMID 27590274, 2016). "CXCL1 acts as a neutrophil chemoattractant and induces hepatic sinusoidal thrombosis, portal hypertension, and fibrosis." (PMID 37152902, 2023). "It has been found that mechanical stretch increases the expression of CXCL1 in LSECs by activating Piezo channels, recruits neutrophils, generates sinusoidal microvessels and promotes portal hypertension and fibrosis." (PMID 37152902, 2023). "CXCL1 exerts its function in liver disease mainly by regulating neutrophils, Kupffer cells and myeloid-derived suppressor cells (MDSCs), and its specific receptor CXCR2 is highly enriched." (PMID 37037815, 2023). "In this section, we will discuss the role of CXCL1 in the major liver diseases, namely non-alcoholic fatty liver disease (NAFLD), alcoholic liver disease (ALD), and hepatitis B virus (HBV) and hepatitis C virus (HCV) infection." (PMID 35806156, 2022). "In liver disease, CXCL1 has been found to have a role in alcoholic liver injury, steatohepatitis, and HCC, while previous studies have not examined the relationship between CXCL1 and ACLF." (PMID 34395462, 2021). "CXCL1 release recruits neutrophils that drive microthrombi formation and promote portal hypertension." (PMID 31998732, 2019). "In liver biopsies of patients with alcoholic hepatitis, a Spanish research group recently described up-regulation of CXCL1 expression in correlation with neutrophilic infiltration and the severity of portal hypertension." (PMID 24260493, 2013). "Previous research has shown that in the liver, CXCL1 derived from hepatic sinusoidal endothelial cells can recruit and generate NETs, promoting microthrombus formation in the liver sinusoids and exacerbating portal hypertension." (PMID 40309357, 2025). "Some studies showed that several liver diseases could induce the high expression of CXCL1 in hepatocytes and hepatic astrocytes and eventually lead to tumor genesis, development, invasion, metastasis, and poor prognosis." (PMID 35401213, 2022). "In addition, the pathogenic role of other chemokines such as CCL2 (MCP-1), CCL17, CCL11, CCL20 and CXCL1 in liver diseases remains unclear and requires further investigation." (PMID 32641985, 2020). "Patients with alcohol-induced cirrhosis were significantly more often carriers of the CXCL1 rs4074 A allele (65.3%) than alcoholics without liver disease (54.8%, OR=1.55; 95%CI=1.025-2.350; p=0.04) and healthy controls (53.8%, OR=1.62; 95%CI=1.212-2.151; p=0.001)." (PMID 24260493, 2013). "Altogether, our data indicate that NTBC therapy does not completely resolves HT1-driven liver disease and supports the sustained risk to develop HCC over time as different HCC markers, including Moxd1, Saa, Mt, Dbp and Cxcl1, were significantly increased under NTBC." (PMID 36980965, 2023). "Similarly, CXCL1 and CXCL9 have chemotactic activities and roles in angiogenesis, inflammation and tumor genesis, CXCL12 is related to the HCC metastatic network by recruiting endothelial cell tumor progenitors, and PECAM-1 reflects the liver disease progression." (PMID 26226632, 2015).
breast tumor (17 papers, 2014 to 2025). "The translational relevance of our findings is demonstrated by transcriptomic analyses of human breast tumor tissues, which reveal positive associations between CXCL1 expression and body mass index, poor survival, and a MDSC gene signature." (PMID 33123173, 2020). "CXCL1 in breast tumors causes angiogenesis by acting directly on endothelial cells." (PMID 37108425, 2023). "CXCL1 expression in CAF is also associated with a decrease in TGF-β levels in breast tumors." (PMID 37108425, 2023). "High CXCL1 expression in breast tumors may be associated with either a worse or better prognosis." (PMID 37108425, 2023). "At the same time, the expression of the receptor for TGF-β, i.e., TβRII, is downregulated in breast tumors, resulting in an increase in CXCL1 expression in the tumor." (PMID 37108425, 2023). "It is estimated that 7.5% of primary breast tumors have CXCL1 gene amplification, while in lymph node and lung metastases, the percentage is around 20%." (PMID 37108425, 2023). "CXCL1 expression in breast tumors is also significantly influenced by intercellular signaling and secretory factors." (PMID 37108425, 2023). "Similar roles for CXCL1/CXCL8 and their receptors in inducing EMT were implicated in several other publications of breast tumor cells." (PMID 32582148, 2020). "There was a statistically positive correlation between CXCL1 and pERK expression within the immune cells inside the breast tumor." (PMID 33256011, 2020). "The Ras/MAPK transcriptional signature was highly associated with expression of CXCL1/2/8 and CSF1/2/3 across TNBC/basal-like breast tumors, while T cell–recruiting CXCR3 chemokines were negatively associated with Ras/MAPK activity." (PMID 32634121, 2020). "CXCL1 promotes breast tumor growth, metastasis and chemo-resistance through recruitment of Gr1+ myeloid cells, and by directly signaling to cancer cells." (PMID 26252654, 2015). "In summary, CAFs overexpress CXCL1, a chemokine that promotes the progression and drug resistance of breast tumors." (PMID 26252654, 2015). "Stromal CXCL1 protein expression was positively expressed in all tumors examined, while the RNA was expressed in a small subset of breast tumor samples." (PMID 25344051, 2014). "Immunostaining analysis of breast tumor tissues indicated that increased CXCL1 expression inversely correlated with expression of TGF-β, phospho-SMAD2 and phospho-SMAD3." (PMID 25344051, 2014). "Fibroblasts are important cellular components of the breast tumor microenvironment, and recent studies indicate that this cell type is a potential source of CXCL1 expression in breast tumors." (PMID 25344051, 2014). "It would be of interest to conduct further studies on stromal CXCL1 expression on breast tumor tissues from patients treated with chemotherapies, and conduct functional studies in animal models." (PMID 25344051, 2014). "Notably, the anti-cancer effect of TPCA-1 was partially attributed to CXCL1 inhibition since CXCL1 overexpressing EV-dead (EV-deadrCXCL1) reduced the inhibitory effect of TPCA-1 on EV-dead-induced breast tumor growth and metastasis." (PMID 38654356, 2024). "TAM are also responsible for CXCL1 production in breast tumors." (PMID 37108425, 2023). "BMI is positively correlated with CXCL1 expression levels in breast tumors." (PMID 37108425, 2023). "Taken together, XPS could suppress breast tumor growth and breast CSCs activity in vivo by modulating TAMs/CXCL1 pathway." (PMID 31803057, 2019). "As CXCL1 is increasingly shown to play important roles in tumor recurrence and chemoresistance, further studies on the impact of CXCL1 expression on the breast tumor microenvironment will aid in the development of novel anti-cancer therapies to combat drug resistant tumors." (PMID 25344051, 2014). "In breast tumors, cancer-associated fibroblast (CAF) may be the main source of CXCL1." (PMID 37108425, 2023). "It is possible that microRNA levels in breast tumor tissues may affect CXCL1 RNA levels." (PMID 25344051, 2014).
breast tumor (continued). "In breast tumors, SETD2 expression is downregulated compared to healthy tissue, and thus CXCL1 expression is upregulated." (PMID 37108425, 2023). "The dual roles of chemokines in the senescence context are nicely exemplified by a study on human pituitary tumor-transforming gene 1 (PTTG-1)-driven expression of CXCL1 and CXCL8 in breast tumor cells." (PMID 32582148, 2020). "This notion is backed by our transcriptomic analyses, which shows a positive correlation between CXCL1 expression and BMI, poor survival, and a MDSC expression score in human breast tumor tissues." (PMID 33123173, 2020). "The clinical relevance of this pathway is illustrated by our transcriptomic data showing high concordant expression of CXCL1 with increasing BMI, poor survival, and a MDSC expression score in human breast tumors." (PMID 33123173, 2020). "Modulation of genes related with invasion, metastasis and chemoresistance (ICAM-1, CXCL1, TNFAIP3, IL8) were confirmed in additional doxorubicin-treated cell lines and fresh primary human breast tumors." (PMID 24344116, 2014). "Additionally, immunofluorescence analysis of breast tumours revealed that BHS synergized with paclitaxel to significantly decrease the expression of TSG101 and CXCL1, indicating that paclitaxel‐induced EV‐Apo biogenesis and CXCL1 secretion were suppressed." (PMID 39051750, 2024). "There are reports that CXCL1 expression in breast tumors is lower than in normal tissue, although some studies show that CXCL1 expression in breast tumors does not differ from healthy tissue." (PMID 37108425, 2023). "Immunofluorescence assay indicated that ADQ significantly decreased the CD206 (M2 phenotype marker) and CXCL1 expression levels in breast tumor tissues, suggesting that ADQ was able to significantly inhibit TAM infiltration and attenuate CXCL1 expression in vivo." (PMID 34461944, 2021). "Other chemokines (CXCL1, CCL9) were also connected to induction of MMPs in breast tumor cells." (PMID 32582148, 2020). "Therefore, CXCL1/2 and CXCL8 may act in a synergistic manner to control neutrophil trafficking to breast tumors." (PMID 40833805, 2025). "Additionally, immunofluorescence analysis of breast tumours showed that BHS synergized with paclitaxel to significantly decrease the expression levels of CD81, CXCL1, and CD204, suggesting that BHS suppressed paclitaxel‐induced EV‐Apo biogenesis, CXCL1 secretion, and TAM infiltration." (PMID 39051750, 2024).
injury (17 papers, 2012 to 2026). Damage inflicted on the body as the direct or indirect result of an external force, with or without disruption of structural continuity. "Moreover, we demonstrated that dasatinib treatment effectively ameliorated inflammatory manifestations in SP-induced acute lung injury in mice, characterized by the increased levels of IL-1α, IL-1β, CXCL1, neutrophils, and M1 macrophages." (PMID 37705538, 2023). "In addition, IL-17, a newly discovered pro-inflammatory cytokine, is highly abundant in drug-induced liver injury and produces the chemokines CXCL1 and MIP-2." (PMID 29554950, 2018). "CXCL1 is known to be important in neutrophil recruitment in bleomycin-induced acute lung injury." (PMID 26154059, 2015). "In acute lung injury, CXCR2 ligands (including CXCL1/2/3) exhibit chemotactic activity toward polymorphonuclear leukocytes." (PMID 41378129, 2025). "MKC (murine KC, CXCL1), MCP-1 (CCL2) and RANTES (CCL5) are chemokines that are involved in the pathogenesis of acute lung injury." (PMID 38474386, 2024). "Hepatocyte death is reduced by 5 ng/mL each of CXCL1 and CXCL2, and CXCL2 promotes liver regeneration and protects against adenovirus- and acetaminophen-induced liver injury." (PMID 39619227, 2023). "Our results demonstrate that microglia reveal an early pro-inflammatory response demonstrated by an upregulation of CXCR2, CXCL1 and NLRP3 gene expression following LPS-sensitized HI brain injury in neonatal rats." (PMID 33123073, 2020). "BAL levels of CXCL1, CXCL2, IL-1β, TNFα and TGFβ were increased during the early phase, while IGF-1 levels were significantly increased in the later phase, suggesting that IGF-1 is involved in the resolution processes of acute lung injury." (PMID 41431237, 2026). "For example, C-X-C motif chemokine ligand 1 (CXCL1), also known as GroA, is upregulated within the first 24 h after hospital admission in trauma patients who develop ileus compared with CXCL1 levels in trauma patients who do not develop ileus." (PMID 35805922, 2022). "Aerobic exercise can also modulate the inflammatory/anti-inflammatory and oxidative/antioxidative balance in the early stage of LPS-induced lung injury, which leads to a decrease in the release of inflammatory mediators such as TNF-α, IL-6, IL-10, IL-1β, IL-17, GM-CSF, and CXCL1/KC." (PMID 36456896, 2022). "Similarly, we also found that, compared to sham rats, IL-1β, CXCL1, CXCL11, CCL2, and transcription factor (Spil/Pu.1, Runx3, and IκBz) are obviously elevated at 7 days following nerve injury." (PMID 31708740, 2019). "CXCL1/2 are major neutrophil chemoattractants that transduce signals by binding to the receptor, CXCR2 (56, –, 58), which mediates neutrophil recruitment and migration, as well as inflammation, in acute respiratory distress syndrome and acute lung injury (38, 54, –, 56, 59, 60)." (PMID 36005818, 2022). "Genes that encode inflammatory cytokines (such as TNF and IL1), chemokines (such as CCL2, CXCL1, CXCL2, and CXCL3) and cell proliferation-related proteins (such as CycD and CycE) were downregulated when Cyp2c29 was overexpressed in a mouse model of liver injury." (PMID 32587777, 2020).
peritonitis (17 papers, 2013 to 2024). Inflammation of the peritoneum (tissue that lines the abdominal wall and covers most of the organs in the abdomen). "For example, neutrophils from pneumonitis and peritonitis (as well as healthy and arthritic blood) exhibited a predominance of Cxcr2, encoding the receptor for key neutrophil recruitment chemokines KC (CXCL1) and MIP2 (CXCL2)." (PMID 34001893, 2021). "Given that CXCL1 production by macrophages has been shown to promote neutrophil infiltration in a peritonitis model, we next asked if HIF deficiency promoted CXCL1 production by macrophages." (PMID 30455703, 2018). "Recently, we have characterized the mechanism by which IL-17 induces CXCL1 in HPMCs and how this contributes to neutrophil recruitment during peritonitis." (PMID 35185912, 2022). "CXCL1 can be induced in HPMCs in vitro not only in response to recombinant IL-17, but also to IL-17-containing peritoneal effluent from PD patients with peritonitis." (PMID 35185912, 2022). "The injection of MSU or CPP crystals caused a leucocyte infiltration and an increase in IL-1β, CXCL1, IL-6, TNF-α, and VEGF in lavage fluids from mice with peritonitis, which diminished in the presence of BPI." (PMID 36361854, 2022). "Acute PMN migration in models of zymosan-induced peritonitis or ligated intestinal loops induced by intraluminal administration of PMN-chemokine CXCL1 was increased over 2-fold in MPO KO compared to wild type (WT) mice." (PMID 33959129, 2021). "CXCL1 was critical for the retention and accumulation of neutrophils in omFALCs during Zymosan-induced peritonitis." (PMID 32294409, 2020). "Radiation-resistant stromal-derived CXCL1 is important in the control of bacterial infection during peritonitis." (PMID 32294409, 2020). "Blockade of CXCL1 inhibited the recruitment and aggregation of neutrophils at FALCs during zymosan-induced peritonitis." (PMID 32294409, 2020). "The migration of neutrophils into the peritoneal cavity during induction of peritonitis has been described to be mediated via CXCL1 and CXCL2." (PMID 28881574, 2017). "As seen in air-pouch and peritonitis models, CXCL-1 expression and subsequent neutrophil influx at wound sites were increased in hspB1del/del mice compared to wild-type mice." (PMID 24143227, 2013). "We then tested whether CXCL1 was involved in the accumulation of neutrophils at omFALCs during peritonitis, using an anti-CXCL1 blocking antibody." (PMID 32294409, 2020). "The Cxcl13+ FALC cover cell cluster was distinguished by the expression of the monocyte chemoattractants Ccl2 and Ccl7 and the neutrophil chemoattractants Cxcl1 and Cxcl10, suggesting a role for these cells in orchestrating the recruitment of inflammatory cells during peritonitis." (PMID 32294409, 2020). "To test if observed defective expression of Cxcl1 and Cxcl2 in lmp7−/− mice has an impact on recruitment of inflammatory cells during peritonitis, we measured the percentage of neutrophils in peritoneal lavages 4 h after intraperitoneal injection of thioglycollate." (PMID 28881574, 2017). "Taken together, these reports support our hypothesis that increased chemerin levels observed in the Ccrl2−/− mice were responsible for increased myeloid cell recruitment via the increased production of inflammatory mediators such as CXCL1 during sterile peritonitis." (PMID 29209334, 2017). "In addition, the concentration of pro-inflammatory cytokines TNF-α, IL-6, IL-1β, KC (CXCL1) and MIP-2 (CXCL2) within the peritoneal lavage also demonstrated that SEMA7A holds protective potential during peritonitis." (PMID 38094294, 2023). "Interestingly, we found that in a murine model of sterile peritonitis, both NSlit2 and a pharmacologic inhibitor of macropinocytosis, EIPA, attenuated the MDP-induced CXCL1 secretion, locally in the peritoneal exudate, and systemically in serum." (PMID 32807784, 2020).
peritonitis (continued). "In addition, in the analysed group of 43 PD patients, peritoneal expression of CXCL1 did not significantly correlate with the duration of therapy, the number of peritonitis episodes, or the total dialysis exposure to glucose." (PMID 35185912, 2022).